FMO5 (flavin containing dimethylaniline monoxygenase 5)
Description:
Acts as a Baeyer-Villiger monooxygenase on a broad range of substrates. Catalyzes the insertion of an oxygen atom into a carbon-carbon bond adjacent to a carbonyl, which converts ketones to esters. Active on diverse carbonyl compounds, whereas soft nucleophiles are mostly non- or poorly reactive. In contrast with other forms of FMO it is non- or poorly active on 'classical' substrates such as drugs, pesticides, and dietary components containing soft nucleophilic heteroatoms (Probable). Able to oxidize drug molecules bearing a carbonyl group on an aliphatic chain, such as nabumetone and pentoxifylline. Also, in the absence of substrates, shows slow but yet significant NADPH oxidase activity. Acts as a positive modulator of cholesterol biosynthesis as well as glucose homeostasis, promoting metabolic aging via pleiotropic effects (By similarity).
Synonyms: hBVMO1
Tractability: Antibody: UniProt predicts a signal peptide or a membrane-spanning region. PROTAC: its protein half-life has been measured.
Target class: Enzyme; Oxidoreductase
Gene: Protein-coding gene on chromosome 1 (147,175,351 to 147,243,050, reverse strand). Ensembl gene ENSG00000131781.
Subcellular location: Microsome membrane; Endoplasmic reticulum membrane
Subcellular location (Human Protein Atlas): Cytosol; Endoplasmic reticulum
Gene Ontology:
Molecular function: monooxygenase activity; N,N-dimethylaniline monooxygenase activity; NAD(P)H oxidase H2O2-forming activity; flavin adenine dinucleotide binding; NADP binding
Biological process: xenobiotic metabolic process; regulation of cholesterol metabolic process
Cellular component: endoplasmic reticulum; endoplasmic reticulum membrane
Genetic constraint (gnomAD): Loss-of-function variants: 35 observed, 33.02 expected, observed/expected ratio (o/e) 1.06, 90% interval 0.81 to 1.4. The upper end of that interval is the gene's LOEUF score, 1.4, which puts it in group 5 of 6, group 1 being the genes least tolerant of losing a copy. Missense variants: 560 observed, 587.08 expected, observed/expected ratio (o/e) 0.95, 90% interval 0.89 to 1.02. Synonymous variants: 170 observed, 205.6 expected, observed/expected ratio (o/e) 0.83, 90% interval 0.73 to 0.94.
Gene-disease validity (ClinGen):
ClinGen rates the evidence that FMO5 causes each of these diseases.
congenital heart disease (autosomal dominant): Disputed. A heart disease that is present at birth.
Homologues: Orthologues: chimpanzee FMO5 (99% identical), macaque FMO5 (97% identical), guinea pig FMO5 (87% identical), rabbit FMO5 (85% identical), rat Fmo5 (84% identical), mouse Fmo5 (84% identical), pig FMO5 (75% identical), dog FMO5 (71% identical), tropical clawed frog fmo5.2 (63% identical), Caenorhabditis elegans fmo-3 (42% identical), Caenorhabditis elegans fmo-5 (42% identical), Caenorhabditis elegans fmo-1 (41% identical), and 2 more. Paralogues in human: FMO2 (56% identical), FMO3 (53% identical), FMO1 (51% identical), FMO4 (51% identical), FOXRED2 (20% identical).
Diseases named in the same sentence as FMO5 in open-access papers:
FMO5 is named in the same sentence as 399 diseases in open-access papers, as found by Europe PMC text mining. Sharing a sentence is not in itself a finding about the gene and the disease. The quoted sentences say what the papers report.
Obesity (68 papers, 2011 to 2026). Accumulation of substantial excess body fat. "Our results implicate FMO5 as a regulator of body weight and of glucose disposal and insulin sensitivity and, thus, identify FMO5 as a potential novel therapeutic target for obesity and insulin resistance." (PMID 28646079, 2017). "Given the need to find an effective and safe anti-obesogenic agent for a world population where obesity incidence is increasing rapidly we wished to understand if genetic variation in human FMO5 would lead to any of the clinical and metabolic phenotype changes seen in the Fmo5−/− mice." (PMID 40924250, 2025). "Thus, FMO5 is identified as a potential novel therapeutic target for obesity and insulin resistance." (PMID 28646079, 2017). "Increased plasma concentrations of RBP4 are correlated with obesity and insulin resistance, and hepatic depletion of Retsat decreases glycolytic flux and de novo lipogenesis, consistent with decreased expression of these genes contributing to the metabolic phenotype of Fmo5-/- mice." (PMID 37267233, 2023). "Fmo5−/− mice share some characteristics of a RELMβ knockout mouse: both are protected from diet-induced obesity, and that protection is independent of diet-induced changes in intestinal microbiota." (PMID 28646079, 2017).
type 2 diabetes (29 papers, 2012 to 2024). "This suggests strongly that the reduction in the expression of FMO5 in type-2 diabetics is a response to this aberrant metabolic condition in an attempt to restore homeostasis." (PMID 26049045, 2015). "In liver biopsies of type-2 diabetics, FMO5 was one of 134 genes found to be repressed." (PMID 26049045, 2015).
colorectal cancer (6 papers, 2017 to 2023). A primary or metastatic malignant neoplasm that affects the colon or rectum. "The overexpression of FMO5 was found in colorectal cancer (CRC) tissue, and FMO5 served as an independent prognostic factor for the survival of CRC." (PMID 37274237, 2023).
bladder cancer (2 papers, 2023 to 2024). "Ankfn1, Gstt2, Plec, Gphn, Fmo5, Cmss1, Ahnak, Mecom, Slc2a1, Gsta4, Kras, Peak1, and Hmga2 were associated with worse disease-free survival in bladder cancer patients." (PMID 39769061, 2024). "An 11-gene signature (Hmga2, Peak 1, Kras, Slc2a1, Ankfn1, Ahnak, Cmss1, Fmo5, Gphn, Plec, Gstt2) had the most substantial impact on disease-free survival in bladder cancer patients." (PMID 39769061, 2024).
cervical cancer (2 papers, 2019 to 2025). A primary or metastatic malignant neoplasm involving the cervix. "According to our findings, the CHD6 gene exhibited higher expression than the RIMS1, MORC4, FMO5, TIAM1, and other genes in cervical cancer." (PMID 40847033, 2025).
Cirrhosis (2 papers, 2019 to 2021). A chronic disorder of the liver in which liver tissue becomes scarred and is partially replaced by regenerative nodules and fibrotic tissue resulting in loss of liver function. "Targets affected only by NAFLD-associated cirrhosis were CYP2C8,MGST1, MGST3, UGT2B4, FMO5, and BSEP, while targets that showed asignificant reduction only with cancer-associated cirrhosis were CYP2E1and UGT1A6." (PMID 34428046, 2021). "Wealso quantified nine non-CYP and non-UGT metabolizing enzymes, residentin the endoplasmic reticulum, in all stages of cirrhosis severity,of which, MGST1, MGST3, and FMO5 are reported for the first time incirrhosis." (PMID 34428046, 2021).
microcephaly (1 paper, 2023). A congenital or acquired developmental disorder in which the circumference of the head is smaller than normal for the person's age and sex. "BCL9, FMO5, and GPR89B deletions related to microcephaly are also overrepresented in DD." (PMID 37486921, 2023).
infection (209 papers, 2006 to 2026). The state of being infected such as from the introduction of a foreign agent such as serum, vaccine, antigenic substance or organism. "Remarkably, mutations of either cofactor binding motif caused infection survival defects that were barely weaker than that of null fmo-2/FMO5 mutants." (PMID 33978570, 2021). "To determine the physiological relevance of fmo-2/FMO5 during infection, we examined mutants homozygous for an fmo-2/FMO5 deletion predicted to result in a null allele (C. elegans Deletion Mutant Consortium, 2012)." (PMID 33978570, 2021). "Upon infection, both gain-of-function mutants exhibited further fmo-2/FMO5 induction, reaching higher fmo-2/FMO5 expression than wild type controls." (PMID 33978570, 2021). "Simultaneous deletion of nhr-49/PPARA and fmo-2/FMO5 resulted in similarly impaired infection survival as the single mutants, suggesting that nhr-49/PPARA and fmo-2/FMO5 function in the same pathway." (PMID 33978570, 2021). "Because hlh-30/TFEB and nhr-49/PPARA contributed to both infection-specific fmo-2/FMO5 induction and each other’s expression, we examined their genetic interactions." (PMID 33978570, 2021). "Deletion of fmo-2/FMO5 severely compromised infection survival, thus identifying the first FMO with innate immunity functions in animals." (PMID 33978570, 2021). "Together, these data indicated that FMO-2/FMO5 catalytic activity may be specifically required for host defense against infection." (PMID 33978570, 2021). "Thus, it is possible that FMO-2/FMO5 is an infection-specific NADPH oxidase that generates H2O2 with antimicrobial and signaling functions." (PMID 33978570, 2021). "In addition, we found that intestinal-restricted fmo-2/FMO5 overexpression was sufficient to boost infection survival." (PMID 33978570, 2021). "In addition, we found that loss of FMO-2/FMO5 causes a severe defect in infection survival without affecting longevity." (PMID 33978570, 2021). "As the most highly induced infection-specific gene in hlh-30/TFEB mutants, fmo-2/FMO5 attracted our attention." (PMID 33978570, 2021). "During infection, NHR-49/PPAR-α appeared to be essential for fmo-2/FMO5 expression in the whole animal, while hlh-30/TFEB was partially dispensable in the intestine and pharynx." (PMID 33978570, 2021). "Therefore, elucidation of mechanisms of host defense mediated by FMO-2 in nematodes and FMO5 in mammals will provide fundamental insight into evolutionarily conserved mechanisms of host defense against infection and identify therapeutic opportunities for infections and inflammatory diseases." (PMID 33978570, 2021). "Deletion of fmo-2/FMO5 did not affect the induction of the nine most highly induced infection-specific signature genes." (PMID 33978570, 2021).
tumor (96 papers, 2009 to 2026). "According to the mechanism of miRNA, these miRNAs which bind to CAMK2N1 should be tumor-suppressive miRNAs, and these miRNAs which bind to FMO5 are tumor-promoting." (PMID 36092901, 2022).
psychiatric disorder (5 papers, 2016 to 2024). A disorder characterized by behavioral and/or psychological abnormalities, often accompanied by physical symptoms. "Our study provides evidence that the same genes (e.g., MC4R, FIBIN, and FMO5) harbor both common and rare variants affecting body size and that anthropometric traits share genetic loci with developmental and psychiatric disorders." (PMID 28963451, 2017).
FMO5 also shares sentences with these, for which no sentence is quoted: chronic granulomatous disease (288 papers); Hypertension (238); endothelial dysfunction (210); diabetes (180); Hyperglycemia (130); cancer (123); atherosclerosis (110); Insulin resistance (50); cardiovascular diseases (49); Stroke (44); heart failure (42); diabetic nephropathy (40); Sepsis (40); ischemia (37); cardiac hypertrophy (36); bacterial infection (26); metabolic syndrome (25); Cognitive impairment (24); neurodegenerative disease (24); Parkinson disease (24); Alzheimer disease (23); kidney diseases (23); Cerebral ischemia (22); COVID-19 (22); fungal infections (22); myocardial infarction (20); breast carcinoma (19); Immunodeficiency (18); Arthritis (17); colitis (17).
A further 359 diseases each share a sentence with FMO5 in 17 papers or fewer.